DNAJC5B (DnaJ heat shock protein family (Hsp40) member C5 beta)
Synonyms: CSP-beta; MGC26226
Tractability: No criterion of Open Targets' tractability assessment is met for any kind of drug.
Gene: Protein-coding gene on chromosome 8 (66,021,553 to 66,101,252, forward strand). Ensembl gene ENSG00000147570.
Subcellular location: Membrane
Gene Ontology:
Molecular function: protein binding
Cellular component: cytoplasm; membrane
Genetic constraint (gnomAD): Loss-of-function variants: 23 observed, 24.03 expected, observed/expected ratio (o/e) 0.96, 90% interval 0.69 to 1.36. The upper end of that interval is the gene's LOEUF score, 1.36, which puts it in group 5 of 6, group 1 being the genes least tolerant of losing a copy. Missense variants: 236 observed, 246.19 expected, observed/expected ratio (o/e) 0.96, 90% interval 0.86 to 1.07. Synonymous variants: 99 observed, 93.91 expected, observed/expected ratio (o/e) 1.05, 90% interval 0.89 to 1.25.
Homologues: Orthologues: chimpanzee DNAJC5B (99% identical), macaque DNAJC5B (97% identical), pig DNAJC5B (89% identical), mouse Dnajc5b (89% identical), rat Dnajc5b (88% identical), guinea pig DNAJC5B (85% identical), rabbit DNAJC5B (85% identical), dog DNAJC5B (80% identical), tropical clawed frog dnajc5b (73% identical), zebrafish dnajc5b (68% identical), Drosophila melanogaster Csp (52% identical), Caenorhabditis elegans dnj-14 (40% identical), and 9 more. Paralogues in human: DNAJC5 (66% identical), DNAJC5G (39% identical), DNAJC18 (36% identical), DNAJC13 (34% identical), DNAJC10 (33% identical), DNAJC21 (33% identical), DNAJC11 (29% identical), DNAJC16 (27% identical), DNAJC7 (24% identical), DNAJC1 (23% identical), DNAJC14 (23% identical), DNAJC17 (22% identical), and 8 more.
Diseases named in the same sentence as DNAJC5B in open-access papers:
DNAJC5B is named in the same sentence as 6 diseases in open-access papers, as found by Europe PMC text mining. Sharing a sentence is not in itself a finding about the gene and the disease. The quoted sentences say what the papers report.
osteosarcoma (1 paper, 2024). A usually aggressive malignant bone-forming mesenchymal neoplasm, predominantly affecting adolescents and young adults. "Among the four pivotal HSPs, Kaplan-Meier curves revealed that osteosarcoma patients with high expression levels of DNAJC5B and DNAJC17 exhibited longer OS, though the differences were not statistically significant." (PMID 39430254, 2024).
viral infection (1 paper, 2017). "The increased expression of the HSPB8 and DNAJC5B genes observed in the qPCR array indicated that these proteins either promote HCV replication or were expressed by the cells due to stress resulting from the viral infection." (PMID 29182667, 2017).
tumor (1 paper, 2024). "All six amplifications that led to a substantial increase in expression in tumor samples were also reported as up-regulated HSP when comparing normal and tumor tissues (CCT3, HSPA6, DNAJA3, TRAP1, DNAJC5, and DNAJC5B)." (PMID 38816397, 2024).
DNAJC5B also shares sentences with these, for which no sentence is quoted: esophageal squamous cell carcinoma (1 paper); metastatic melanoma (1); metastatic tumors (1).